MMP9 (matrix metallopeptidase 9)
Diseases named in the same sentence as MMP9 in open-access papers (continued):
Sharing a sentence is not in itself a finding about the gene and the disease.
Cognitive impairment (continued). "An increase in the activity of MMP-9 has been observed in hippocampus while using intracerebroventricular (icv) injections of distinctive Aβ peptides in animal models, which augments cognitive impairment that is induced by Aβ and confirms the results using MMP9 knockout mice and MMP inhibitors." (PMID 33573368, 2021). "Furthermore, increased MMP-9 activity has been detected in the frontal and parietal cortex of postmortem human brains diagnosed with AD and patients exhibiting cognitive deficits." (PMID 34566627, 2021). "Amazingly, a relationship between MMP-9 and cognitive impairment was speculated in mild cognitive impairment (MCI) patients." (PMID 33573368, 2021). "Overexpressed MMP-9 has also been found in the cytoplasm of neurons, neurofibrillary tangles, senile plaques, and vascular walls of the hippocampus and cerebral cortex of AD patients, and inhibiting MMP-9 improves Aβ-mediated cognitive impairment and neurotoxicity in mice." (PMID 32466129, 2020). "Our recent study showed that serum MMP‐9 could be a potential prognostic factor for 3‐month cognitive impairment." (PMID 32431079, 2020). "Based on mRNA expression results, tPA antagonist tPA-stop and MMP-9 antagonist JAJN966, were applied to determine whether JWKXS improved cognitive deficits by regulating neurotrophic factor transformation via tPA and MMP-9." (PMID 30941041, 2019). "Furthermore, these results suggest that the anti-inflammatory effects of minocycline, which was beneficial in reducing white matter injury and cognitive deficits in the same animal model, must be acting through other mechanisms than direct inhibition of MMP-9." (PMID 30533010, 2018). "Based on this data, another possible mechanism for homocysteine-induced cognitive impairment could be the pro-inflammatory mediated increase in MMP9 leading to tight junction degradation, microhemorrhages, and, finally, cognitive impairment." (PMID 30429785, 2018). "Taken together, we hypothesize that another mechanism of homocysteine-induced cognitive impairment involves the inflammatory-MMP9 pathway." (PMID 30429785, 2018). "Furthermore, MMP-9 inhibition was reported to improve Aβ-mediated cognitive impairment and neurotoxicity in mice." (PMID 29459817, 2017). "Studies have shown that MMP9 levels are elevated in the brains of patients with mid- to late-stage AD and increased MMP9 expression in the hippocampus may be involved in the development of Aβ-induced cognitive impairment and neurotoxicity." (PMID 41450541, 2025). "Thus, given CS’s protective effects on synaptic plasticity and the involvement of Erk1/2-MMP-2/MMP-9 signaling in plasticity regulation, we hypothesize that CS protects against fluoride-induced cognitive deficits via the Erk1/2-MMP-2/MMP-9 pathway." (PMID 40804089, 2025). "Future studies should examine whether the associations observed here are specific to the hippocampus, and longitudinal studies are needed to explore the chronological sequence of MMP-9 upregulations, microstructural and macrostructural abnormalities, and cognitive impairments." (PMID 38431757, 2024). "Interestingly, serum MMP-9 level has also been proposed as a significant factor for diagnosing cognitive impairment due to cerebral small vessel disease, which suggests that MMP-9 may be associated with vascular dementia." (PMID 37371326, 2023). "In particular, a relationship between the increase of tissue activation of MMP9 and cognitive impairment has been hypothesized in MCI and AD, revealing that the expression of MMP9 was upregulated in AD patients in neurofibrillary tangles, neuronal cytoplasm, vascular tissue, and amyloid plaques." (PMID 36834642, 2023). "As it is possible to regain a state of plasticity and reverse cognitive deficits by manipulating the onset and closure of ‘critical periods’, regulating MMP-9 activity during CPP may aid in further development of precise and targeted treatments for neurodevelopmental disorders." (PMID 26283917, 2015).
Cognitive impairment (continued). "Most importantly, plasma APOE, MMP9, S100A8, UBR5 PLA2G7, and STAT5B play a potentially crucial role in the progression of cognitive disorders." (PMID 38883967, 2024). "Although several studies reported higher plasma MMP-9 levels and activity in mild cognitive impairment (MCI) and AD, the relationship between MMP-9 and AD pathology remains poorly understood." (PMID 36324151, 2022). "Mean MMP-9 in the non-cognitive impairment group was 280.6 ± 124.2 ng/mL and 392.3 ± 146.1 ng/mL in the cognitive impairment group." (PMID 41542283, 2024). "In a study of 317 patients after acute ischemic stroke, those with post-stroke cognitive impairment or PSD have significantly higher serum levels of MMP-9 when compared to those without." (PMID 39063013, 2024). "-MMP3 levels correlate positively with CSF levels of T-tau and p-tau, but negatively with cognitive impairment.-No significant changes in the CSF concentration of MMP-9 from AD samples compared to controls." (PMID 36980302, 2023). "The correlation analysis demonstrated positive correlations between the total PSWEs and serum CyPA and MMP-9 levels in the present cohort, which also supported PSWEs’ ability to reflect BBB dysfunction, indicating that the effect of BBB dysfunction on cognitive impairment in patients with OSA." (PMID 36585689, 2022). "We used only one test to assess positive symptoms (i.e., MK-801-induced hyperlocomotion), one test to assess cognitive deficits (i.e., novel object recognition test), and two tests to evaluate negative symptoms in Mmp-9 heterozygous mice." (PMID 31555105, 2019). "Mmp-9 heterozygous mice were exposed to the stress procedure; cognitive deficits and negative and positive schizophrenia symptoms were assessed." (PMID 31555105, 2019). "We found no influence of gene × environment interactions on cognitive deficits or positive-like symptoms of schizophrenia, which have been previously shown to be affected by lower MMP-9 activity alone." (PMID 31555105, 2019). "MMP-9 also contributes to Aβ-induced neuronal dysfunction and cognitive impairment by nonspecifically destroying the extracellular matrix and neural membranes." (PMID 22235372, 2011). "Thus, it is possible that changes in MMP-9 levels are not due to animal behavior performance; but are rather the result of mephedrone-induced cognitive impairment." (PMID 33435576, 2021). "While removing the MMP9 gene in the 5xFAD mice did not result in obvious changes in Aβ disposition, it may have prevented the contribution of MMP9 to Aβ-induced cognitive deficits." (PMID 34034683, 2021). "In the present study, adolescent Mmp-9 heterozygous mice, with a genetically lower level of MMP-9, were subjected to resident-intruder psychosocial stress for 3 weeks and then examined in behavioral tests that evaluated cognitive deficits and positive- and negative-like symptoms of schizophrenia." (PMID 31555105, 2019). "Additionally, since both FW and MMP-9 changes are related to cognition in all participants, it might suggest this mechanism’s critical role in cognitive deficits (albeit not necessarily specific to psychosis)." (PMID 38431757, 2024). "The link between MMP-9 and brain structure and function is clinically interesting, given the potential of MMP-9 inhibition and the lack of treatment for cognitive deficits in psychosis." (PMID 38431757, 2024). "Indeed, activation of MMP9, but not of MMP2, was reported in serum and brain samples of patients with mild cognitive impairment and with AD." (PMID 28912710, 2017). "Therefore, even if MMP-9 degrades Aβ or amyloid plaques, it may nonselectively degrade ECM proteins and neural membranes, leading to neuronal dysfunction and cognitive impairment." (PMID 22235372, 2011).
Myocardial fibrosis (73 papers, 2010 to 2025). "Among the MMPs family, MMP2 and MMP9 are two important members associated with myocardial fibrosis regulation." (PMID 40182630, 2025). "The impact of heart base irradiation on pericardial and myocardial fibrosis was also reflected by the enrichment of osteopontin (OPN) signalling via the upregulation of MMP-9 as this is associated with cardiac remodelling and fibrosis." (PMID 40657241, 2025). "Conversely, MMP-9 has been associated with collagen I deposition, thus leading to reactive myocardial fibrosis." (PMID 37122872, 2023). "Glibenclamide reverses ROS production and caspase-1 activity induced by a high-fat diet, downregulates the TGF-β1-pSmad2/3-NLRP3 signaling pathway, inhibits profibrotic factors such as MMP-9, and alleviates myocardial fibrosis." (PMID 40869128, 2025). "Another study also reported that Liquiritin attenuated myocardial fibrosis by reducing the expression of type I collagen, type II collagen, MMP-9, and α-SMA." (PMID 40881586, 2025). "This process downregulated matrixmetallopeptidase 9 (MMP9), thus preventing myocardial fibrosis and exerting acardioprotective effect." (PMID 39618876, 2024). "In AMI rat models, Sal-B selectively inhibits MMP-9 activity, effectively augments left ventricular wall thickness, enhances cardiac contractility, and attenuates myocardial fibrosis." (PMID 39741628, 2024). "It reduced the expression of IL-6, IL-1β, and matrix MMP9, inhibited cell division and proliferation to inhibit myocardial fibrosis." (PMID 38469405, 2024). "TIMP-1 can specifically inhibit the activity of MMP-9 and alleviate the degradation of extracellular matrix collagen, thus improving myocardial fibrosis." (PMID 36820397, 2023). "Matrix metalloproteinase MMP9 plays a key role in myocardial fibrosis and has also been shown to induce a significantly higher inflammatory response in atrial issues of AF patients." (PMID 38357157, 2023). "While a neutralizing antibody against IL-22 led to increased COL1-A1, COL3-A1, MMP9 expression, and intensified myocardial fibrosis in DCM mice, suggesting that IL-22 protects the myocardium by inhibiting myocardial fibrosis." (PMID 36827455, 2023). "In our study, increased levels of MMP-9 plasma levels are consistent with myocardial fibrosis consequent to collagen interstitial accumulation." (PMID 37122872, 2023). "Zhigancao decoction significantly reduced MMP-9 (matrix metalloproteinase-9) protein expression in AF rabbits and attenuated myocardial fibrosis, shortened field action potential duration." (PMID 37608811, 2023). "CTLA-4 blocking agents also increase myocardial fibrosis by modulating the expression of galectin-3, collagen 1, and matrix metalloproteinase 9 (MMP-9)." (PMID 37305530, 2023). "Moe GW reported inhibiting MMP9 expression in canine AF model improved cardiomyocyte hypertrophy and reduced myocardial fibrosis, as well as reduced AF duration." (PMID 35697725, 2022). "Experiments showed that Danhong injection can reduce the blood lipid level, inhibit the expression of MMP9, prevent poor myocardial remodeling, reduce myocardial fibrosis and improve myocardial function." (PMID 36699083, 2022). "Myocardial fibrosis and expression of galectin-3, pro-collagen 1-α and MMP-9 were increased after treatment with all ICIs." (PMID 36158826, 2022). "Cytokines are released, which exacerbate inflammation response and other remodeling markers in myocardial fibrosis (MFs), such as MMP-9." (PMID 35140803, 2022). "Collagen 1 is considered to be the decisive factor leading to myocardial fibrosis, and MMP9 has also been proved to be an important reason for extracellular matrix remodeling after MI, which are closely related to left ventricular remodeling." (PMID 36699092, 2022). "In a previous study, they also showed that CsA caused intense myocardial fibrosis and the increase in MMP-2, while MMP-1 and MMP-9 levels were unchanged." (PMID 35681984, 2022).
Myocardial fibrosis (continued). "In order to further examine the antagonistic effect of AS on myocardial fibrosis after MI, collagen 1 and MMP9 were measured from the RNA and protein layers." (PMID 36699092, 2022). "It is worth noting that when mitochondrial dysfunction occurs, the tricarboxylic acid cycle is inhibited, thereby promoting the remodelling of myocardial fibrosis, which is manifested by upregulation of MMP-9 and collagen I expression." (PMID 34950023, 2021). "To explore the potential mechanism of UCP2 in alleviating myocardial fibrosis, we detected the expression of fibrosis-related proteins (MMP9 and TGF-β) by WB." (PMID 35284500, 2021). "Loss of TIMP3 increased myocardial fibrosis and elevated the expression of MMP2 and MMP9 to a greater extent in iron-overloaded mice." (PMID 34722652, 2021). "The MMP-2 and MMP-9 are the key players of myocardial fibrosis which have been found elevated during ISO-treatment." (PMID 33328989, 2020). "In this study, administration of QSG effectively decreased the level of serum ALD, PIIINP, MMP-2, and MMP-9 that are all closely related to myocardial fibrosis in HF." (PMID 31915683, 2019). "Up-regulation of MMP9, MMP9/TIMP-1 ratio and down-regulation of TIMP-1 were more significant after neutralizing IL-22, associated with myocardial fibrosis exacerbation." (PMID 25547181, 2014). "By inhibiting the expression of HIF-1α, the expression levels of TGF-β1 and MMP-9 decreased accordingly, and the extent of myocardial fibrosis was also reduced." (PMID 25371714, 2014). "Along with its regulation on MMP-9 activity in vivo, SalB treatment also led to a less impaired LV chamber geometry, attenuated myocardial fibrosis, and thus improved heart performance of MI rats." (PMID 20735854, 2010). "IGF2 may also be involved in the progression of myocardial fibrosis by disrupting the TIMP2/MMP9 balance." (PMID 39744430, 2025). "QSYQ inhibited the TGFβ1/Smads signaling pathway and NLRP3 inflammatory vesicle expression, and significantly suppressed monocyte infiltration and macrophage polarization toward M2, thereby inhibiting MMP-2 and MMP-9 expression and ameliorating I/R induced myocardial fibrosis." (PMID 40881586, 2025). "Inflammatory biomarkers such as C-Reactive Protein (CRP), myocardial fibrosis, and hypertrophy biomarkers such as Matrix Metalloproteinase-9 (MMP9) and soluble Suppression of Tumorigenicity 2 (sST2) have been introduced as promising biomarkers for LVR prediction." (PMID 39264503, 2025). "The level of MMP-9 is positively correlated with the severity of myocardial fibrosis." (PMID 36820397, 2023). "HIF-1α can increase the expression of matrix metalloproteinases (MMPs) and transforming growth factor (TGF)-β in AF through promoting atrial fibrosis, and inhibiting the expression of HIF-1α can decrease the levels of TGF-β and MMP-9 accompanied by the less myocardial fibrosis in rabbit models." (PMID 38274270, 2023). "Except for GAL-3 and MMP-9, patients with AF had higher levels of proteins associated with myocardial fibrosis as compared to those without co-existing AF." (PMID 36337899, 2022). "Moreover, MI promoted myocardial fibrosis dramatically, by increasing collagen deposition and upregulated the expression of fibrotic markers including MMP9, collagen type I, and α-SMA, the effects of which were alleviated by FSTL1 administration." (PMID 34957094, 2021). "Our in vivo results showed that GPR30/G1 activation may be associated with the reduction of TGF-β1 and myocardial fibrosis, which may be related with ERK-regulated MMP-9 expression." (PMID 34803680, 2021). "The data indicate that downregulated MMP9 not MMP2 may partly result in the increased protein level of Col3al, contributing to cardiac fibrosis in DCM, and FTZ alleviated myocardial fibrosis at least partially by increasing the expression of MMP9." (PMID 34621323, 2021).
Myocardial fibrosis (continued). "The results suggest that administration of valsartan inhibited the expression of fibrosis-related proteins TGF-β, MMP-2 and MMP-9, which may reduce the accumulation of collagen and further prevent the enlargement of myocardial fibrosis." (PMID 25823960, 2015). "MI-induced up-regulation of fibrosis-related proteins; MMP2 and MMP9 were also suppressed by valsartan, indicating that valsartan may attenuate myocardial fibrosis after MI, consistent with in vitro results." (PMID 25823960, 2015). "Furthermore, HIF-1α can be involved in myocardial fibrosis formation by regulating the MMP-9 expression level." (PMID 25371714, 2014). "Furthermore, the experimental results suggested that GZD could downregulate the expression levels of IL-6, IL-1β, CCL2, MMP-2, and MMP-9, thus inhibiting the inflammation and myocardial fibrosis in Dahl salt-sensitive rats." (PMID 33906674, 2021). "Mmp9 deletion may attenuate age-related myocardial fibrosis and diastolic dysfunction." (PMID 32321550, 2020). "However, whether HIF-1α is involved in myocardial fibrosis, and the associations between HIF-1α, transforming growth factor-β1 (TGF-β1) and matrix metalloproteinase-9 (MMP-9) remain unknown." (PMID 25371714, 2014). "MMP9 expression increases in AMI patients under hypoxic conditions, resulting in accelerated collagen degradation, myocardial fibrosis, compensatory ventricular dilation, and ventricular remodeling." (PMID 39264503, 2025). "Inhibition of the ERK1/2 pathway has a protective effect against LPS-induced myocardial fibrosis, with a notable reduction in the expression of MMP-2 and MMP-9." (PMID 40332776, 2025). "VDR knockout mice with myocardial fibrosis have higher expression levels of matrix metalloproteinase-2 (MMP-2) and matrix metalloproteinase-9 (MMP-9) and lower expression levels of tissue inhibitors of metalloproteinase-1 (TIMP-1)." (PMID 36771445, 2023). "The results demonstrated fibrotic changes, and qPCR and Western blots showed a significant up-regulation of the markers of myocardial fibrosis, including TGF-β1, α-SMA, COL1, and MMP9." (PMID 37505696, 2023). "In this study, the degree of myocardial fibrosis and the mRNA expression levels of α-SMA, TGF-β, collagen I, collagen III, and MMP9 were evaluated." (PMID 35734399, 2022). "Matrix metalloproteinase 9 (MMP-9) can degrade the extracellular matrix (ECM) components and play a critical role in myocardial fibrosis." (PMID 35140803, 2022). "Taken together, these results favored the notion that GRP30 activation inhibited MMP-9 expression via ERK1/2 signaling to at least partially preserve cardiac function and inhibited myocardial fibrosis in aged female hypertrophied hearts." (PMID 34803680, 2021). "In summary, our results from in vivo and in vitro studies indicated that GPR30 activation inhibited myocardial fibrosis and preserved cardiac function via inhibiting ERK-mediated MMP-9 expression." (PMID 34803680, 2021). "The ultrastructure, degree of myocardial fibrosis, apoptosis index (AI), expression of microRNA-1, expression of microRNA-21, and mRNA of TIMP-1, MMP-9, BCL-2, and Bax of patients were compared and analyzed in each group." (PMID 34957910, 2021). "We further demonstrated that RDN decreased the level of NT-BNP, improved myocardial fibrosis, and decreased the expression of MMP-2 and MMP-9." (PMID 29739333, 2018). "We then analysed the expression of fibrosis-related proteins (MMP2, MMP9 and collagen I) to determine the roles of TGF-β1/Smad and HIF-1α pathways in myocardial fibrosis." (PMID 25823960, 2015). "With the progression from AVMC to DCM, the severity of myocardial fibrosis significantly increased accompanied by up-regulation of COL1-A1, COLA3-A1, MMP9 and ratio of MMP9/TIMP-1 but down-regulation of TIMP-1." (PMID 25547181, 2014).